ADAM12 (ADAM metallopeptidase domain 12)
Diseases named in the same sentence as ADAM12 in open-access papers (continued):
Sharing a sentence is not in itself a finding about the gene and the disease.
tumor (continued). "Expression levels of other activin A target genes, including Adam12, Pmepa1, and Lmcd1—known to be involved in receptor endocytosis, fibrogenesis, and tumor progression —were significantly elevated by activin A (confirming our previous studies), and entirely antagonized by NUCC-555." (PMID 38607090, 2024). "ADAM-12 is a novel regulator of tumor angiogenesis found upregulated in epithelial cancers." (PMID 39358558, 2024). "Likewise, it has been previously shown that ADAM12 urine levels correlate with tumor stage and prognosis in different types of cancer." (PMID 37495855, 2023). "Moreover, we show for the first time in cancer patients that ADAM12 expression is induced by ionizing radiation in both normal and tumor tissues." (PMID 37495855, 2023). "Moreover, the IHC assay demonstrated that the levels of ADAM12, c-Myc, N-cadherin and Snail drastically decreased after silencing ADAM12, whereas E-cadherin markedly increased, suggesting inhibition of tumor growth and the EMT process." (PMID 36717944, 2023). "The frequencies and absolute numbers of ADAM12+ cells decreased at later tumor stages." (PMID 37798557, 2023). "Thus, to investigate the link between ADAM12 expression in cancer cells and in vivo tumor growth following irradiation, we initially compared the number of endothelial cells in WT versus A12−/− tumors." (PMID 37495855, 2023). "Moreover, ADAM12 promotes tumor progression in multiple mouse models and its expression has been linked to chemoresistance." (PMID 37495855, 2023). "We observed that ADAM12+ MSCs (expressing GFP) localized specifically at the tumor margin, a transition zone enriched in stromal cells expressing various levels of PDPN and smooth muscle actin alpha 2 (αSMA+), collagenous ECM, T cells, CD206+ TAMs and blood vessels." (PMID 37798557, 2023). "Because ablation of ADAM12+ cells decreased tumor hypoxia, we asked whether hypoxia affected CAF differentiation toward S1." (PMID 37798557, 2023). "Finally, to assess the role of ADAM12+ MSCs in a spontaneous tumor model, we crossed ADAM12-DTR mice with Rip-Tag2 mice to generate RIP+DTR+ and RIP+DTR– mice." (PMID 37798557, 2023). "While there was a tendency towards an increased number of CD31+ vessels in ADAM12-deficient tumors, the differences were not significant in either the periphery of the tumor or the tumor core." (PMID 37495855, 2023). "However, we discovered that in patients who received RT, a high ADAM12 expression correlated with tumor stage." (PMID 37495855, 2023). "The results revealed that the ADAM12 gene was expressed in various tumours." (PMID 35459884, 2022). "Human ADAM12 exists as soluble (iso) forms that can be detected in the circulation, and serum levels of this protein can serve as non-invasive proxies for stromal activation in tumor tissue." (PMID 35413826, 2022). "The poor prognosis in ADAM12-high patients observed in this study may be due to both the high stromal activation and the tumor promoting properties of activation of growth pathways." (PMID 35413826, 2022). "ADAM12 is a proteolytic glycoprotein that is located almost exclusively in tumour cells." (PMID 35565436, 2022). "Some clinical investigations have revealed that ADAM12 overexpression may lead to increased tumour size and metastasis." (PMID 35565436, 2022). "In microdissected cancer tissue, ADAM12 expression was confined to the tumor stromal fraction." (PMID 35413826, 2022). "(A) ADAM12 expression is elevated in different tumor tissues." (PMID 35094638, 2022). "Signaling pathways involved in the effects of ADAM12 were investigated using the STRING and Metascape interactive online websites to perform a functional enrichment analysis and investigate the potential molecular mechanism of the ADAM12 gene in tumor progression." (PMID 34604068, 2021).
tumor (continued). "First, the relationships between the abundance of tumor-infiltrating lymphocytes and ADAM12 expression levels were investigated to examine which types of TILs might be regulated by the ADAM12 gene." (PMID 34604068, 2021). "It was proven that ADAM12 regulated tumour progression in gene-modified mice models." (PMID 33507683, 2021). "Recently, ADAM12 was reported to play an important role in tumor neovascularization and/or tumor cell extravasation by activating the shedding of several membrane-anchored proteins, such as sonic hedgehog, Delta-like 1, and certain epidermal growth factor receptor ligands." (PMID 34604068, 2021). "Next, we used ImmuCellAI to evaluate the immune infiltration score and the abundance of 24 immune cells from tumor tissues, and then calculated the multiple and single correlation coefficients of ADAM12, MMP1, SERPINE1, PLOD3, and P4HA3 with mRNA expression and immune infiltration score." (PMID 34121340, 2021). "Therefore, ADAM12 is considered correlated with the extracellular matrix and plays a role in tumor progression in the tumor microenvironment; however, these findings require further study for confirmation." (PMID 34604068, 2021). "In addition, overexpression of ADAM12 enhanced the growth and progression of human CRC cells, and knockdown of ADAM12 showed potent anti-tumor activity in our in vivo mouse xenograft model." (PMID 33923541, 2021). "Furthermore, ADAM12 reduces tumor cell apoptosis and promotes tumor growth by redistributing and activating MMP14, resulting in gelatin degradation." (PMID 34604068, 2021). "Furthermore, ADAM12 hypomethylation was associated with a worse outcome in TNBC tissues and was also found in adjacent-to-tumour tissue and, preliminarily, in plasma from TNBC patients." (PMID 32019179, 2020). "We also observed that adjacent-to-tumour samples, without apparent neoplastic cell morphology, harboured a significant loss of ADAM12 methylation compared with non-neoplastic cases (p< 0.05)." (PMID 32019179, 2020). "ADAM-12 and other MMPs, such as 1, 2 and 9, may contribute to the release of mitogens, thereby increasing local aggressiveness and tumour morbidity." (PMID 32386517, 2020). "It interacts with the short secreted isoform of ADAM12, which is overexpressed in many tumor types." (PMID 32664474, 2020). "ADAM12-mediated shedding of BSG could promote tumor progression by stimulating MMP activation and enabling cancer cell invasion." (PMID 31013576, 2019). "In both tumor types we found correlations between high ADAM12 expression and lower KAT2A levels." (PMID 30753595, 2019). "However, of the two isoforms of ADAM12, only the secreted one enhanced the ability of tumor cells to migrate and invade, resulting in a higher incidence of local and distant metastasis in vivo." (PMID 31565100, 2019). "We identified ADAM12 in a previous screen for stromal targets of tumor-derived SHH24." (PMID 30442938, 2018). "Known roles for stromal ADAM12 are manifold: the well characterized function of ADAM12 as a sheddase of growth factor receptor ligands such as EGF can provide a nurturing environment for tumor cells." (PMID 30442938, 2018). "Furthermore, SKBR3/siA12 or MDA-MB-231/siA12 cells treated with 5-FU resulted in an even greater reduction in tumor weight compared with treatment with scramble control and 5-FU or ADAM12 siRNA alone." (PMID 28852196, 2017). "A number of fast evolving, placental genes show tumorigenic or tumor suppression activity (ADAM12, ADAMTS18, CAPN6, EGFL6, HTRA4, LIN28B) and others are involved in disorders associated with epithelial and connective tissues (FBN2) or have immune functions (IL1RL1, PRG2, SIGLEC6)." (PMID 26641094, 2015). "ADAM12 is selectively expressed in GBM tissues where it might be involved in supporting tumor cell proliferation that is mainly sustained by enhanced EGF signaling through EGFR." (PMID 26437223, 2015).
tumor (continued). "Moreover, growing evidences have indicated for ADAM12 an important role in supporting tumor cell adhesion, which is mediated through binding of the cysteine-rich domain of ADAM12 to syndecans, cell surface proteoglycans." (PMID 26437223, 2015). "The finding of a positive correlation between ADAM-12 and VEGF-A121 and VEGF-A165 isoforms, which are proangiogenic, in all tumour samples reinforce the hypothesis of a specific role for ADAM-12 in tumour-associated angiogenic process." (PMID 16495931, 2006). "In accordance, immunohistochemical analysis revealed ADAM-12 production by tumour cells." (PMID 16495931, 2006). "ADAM-12L (membrane-bound long variant) transcripts were overexpressed in tumours when compared to controls, while no expression of short form of ADAM-12 (ADAM-12S) (secreted short variant) was detected in the lung tissues examined." (PMID 16495931, 2006). "Together, these studies highlight the diverse roles of ADAM12 in cancer progression, ranging from its involvement in angiogenesis, metastasis, and therapy resistance to its potential as a prognostic biomarker, thereby warranting further investigation into its clinical relevance across tumour types." (PMID 40427200, 2025). "Furthermore, ADAM12 was also generally highly expressed in almost all types of tumour tissues." (PMID 37082201, 2023). "In addition, CTHRC1 and ADAM12, which were highly expressed in C02_POSTN and C07_MKI67 could promote tumour progression, and affect the infiltration of immune cells and polarization of M2 macrophages." (PMID 38115703, 2023). "Moreover, we showed that ADAM12 expression had a striking effect on disease-free survival and that it correlated with distant recurrence only in patients undergoing RT before surgical removal of the tumor." (PMID 37495855, 2023). "Moreover, it has been indicated that the stimulatory effect of ADAM12 on the migration and invasion of tumour cells is probably dependent on its proteolytic activity, and thus ADAM12 may represent a potential therapeutic target." (PMID 35565436, 2022). "However, only the secreted form of ADAM12 may enhance the ability of tumour cells to migrate and invade as well as stimulate local and distant metastasis in vivo." (PMID 35565436, 2022). "Furthermore, ADAM12 mediated immune cell infiltration in the tumor microenvironment." (PMID 35094638, 2022). "Serum ADAM12 could be a feasible marker to inform on the aggressiveness of the tumor." (PMID 35413826, 2022). "Furthermore, ADAM12 knockdown reveals potent anti-tumor activity in a mouse xenograft model." (PMID 33923541, 2021). "The expression of NOTCH1, a disintegrin and metalloproteinase 12 (ADAM-12), hypoxia-inducible factor 1 alpha (HIF-1α), and heparin-binding epidermal growth factor (HB-EGF) under hypoxic conditions has been implicated in invadopodia formation, tumour invasiveness, and metastasis." (PMID 32386517, 2020). "Furthermore, ADAM-12 increases apoptosis of stromal cell but decreases that of tumor cells." (PMID 30718556, 2019). "Importantly, the increased expression of ADAM12L (0.8±0.9 versus 1.2±1.1, p<0.05) and ADAM12S (0.7±0.9 versus 1±1.3, p<0.05) in breast samples was associated with the presence of metastases supporting evidences for the involvement of ADAM12 in human tumor aggressiveness." (PMID 26407179, 2015). "Elevated ADAM8, ADAM9, ADAM12 and ADAM17 levels were observed in CRC tissues and correlated with more advanced tumor stage, while increased serum ADAM15 concentrations associated with the presence distant metastases." (PMID 41976350, 2026). "Published data show that several ADAMs, including ADAM8, ADAM9, ADAM10, ADAM12, and ADAM17, are overexpressed in tumours." (PMID 40427200, 2025). "To get better insight into the role of ADAM12 and CYP1B1 in the tumor–stroma crosstalk, first, we analyzed the influence of their silencing on RCC cell proliferation." (PMID 39806854, 2025).
tumor (continued). "CD147 is also emerging as a protein capable of regulating cancer hallmarks, such as tumor angiogenesis, a process in which CD147 acts through the regulation of VEGF/VEGFR and ADAM-12." (PMID 39358558, 2024). "The relationship between CD147 and HLA-G is seen in cancer cells where CD147 is emerging as a protein capable of regulating cancer hallmarks, such as tumor angiogenesis, a process in which CD147 acts through the regulation of VEGF/VEGFR and ADAM-12." (PMID 39358558, 2024). "Some of the ADAMs, such as ADAM9, ADAM10, ADAM12, ADAM15, and ADAM17, are frequently upregulated in tumor tissues as well as cancer cell lines, and their expression often correlates with adverse patient survival and/or treatment response." (PMID 37495855, 2023). "In summary, we detected the partial recapitulation of KS tumor microenvironment cell surface protein expression within the xenograft tissues where FLT4, KDR, UNC5A, and ADAM12 mirrored the levels detected in the human KS tumors." (PMID 37046832, 2023). "Here, by Cox modeling, we develop IRS—which combines TMB with CD274, PDCD1, ADAM12 and TOP2A quantitative expression—to predict pembrolizumab rwPFS (648 patients; 26 tumor types; IRS-High or -Low groups)." (PMID 36750617, 2023). "The high ADAM12 gene expression in HCC tissues is remarkably positively related with T stage, pathological stage and residual tumor." (PMID 36843929, 2023). "In particular, ADAM12 is upregulated in both ccRCC tissues and cells and is correlated with gender, TNM stage and tumor grade." (PMID 37370817, 2023). "Here, in correlation with transcriptome data, we demonstrated the detectable protein expression of KDR, FLT4, UNC5A, ADAM12, CD34, and Prox-1 in the human KS tumor microenvironment." (PMID 37046832, 2023). "Selective depletion of such metabolically altered mesenchymal stromal subset, identified by expression of ADAM12, normalized the TME and decreased tumor hypoxia and acidosis, inducing infiltration of activated T cells and inhibition of tumor growth." (PMID 37798557, 2023). "Further suggesting a crosstalk between ADAM12+ MSCs and macrophages, ADAM12+ cells accumulated around MO5 tumors close to CD206+ TAMs, starting in early tumor stages." (PMID 37798557, 2023). "Therefore, targeting ADAM12 may become an alternative strategy for tumor therapy." (PMID 35094638, 2022). "In previous papers, some tumor-promoting genes (like Snail1, Slug, ZEB1/2, MMP2, MMP9, and ADAM12) were found to be modulated by TGF-β." (PMID 35794983, 2022). "Further analysis of differences in the gene expression levels of ADAM12, MMP1, SERPINE1, PLOD3, and P4HA3 between tumor and adjacent normal tissues in 18 cancer types from TCGA were examined." (PMID 34121340, 2021). "cancer cell invasion, including ADAMs (as reviewed above), and interestingly, ADAM12, and MMP2 and 9 are all upregulated by TGF-β1 signaling in tumor metastasis." (PMID 33946495, 2021). "Our analysis identified several genes with recurrent HBV integration, including TERT, MLL4, ADAM12, PREX2, and SCFD2 in tumor tissues." (PMID 34209079, 2021). "We hypothesized that ADAM12 affects some cytokines required for angiogenesis in the tumor microenvironment via specific signaling pathways, such as vascular cell adhesion molecule 1 and vascular endothelial cadherin, and mediates tumor angiogenesis to subsequently promote tumor progression." (PMID 34604068, 2021). "CAF-mediated EMT, which is strongly correlated with the expression of AXL, TWIST2 and ADAM12 from the IMS, can result in biomechanical and biochemical changes that facilitate tumor immune escape, invasion, and metastasis." (PMID 33542239, 2021). "Here we demonstrate that ADAM12 silencing inhibits TNBC cell proliferation and migration in vitro, a finding that is consistent with those of the only study showing tumour-initiation and growth effects of ADAM12 silencing in a TNBC in vivo model." (PMID 32019179, 2020).
tumor (continued). "PD-L1 expression positively correlated with high expression levels of tumor promoting genes such as CD68, ADAM12, FXYD5, S100A11, CD46, and MED19 (and ST1D)." (PMID 33415077, 2020). "To functionally confirm this activation mechanism to drive ADAM12 expression, we treated human stellate cells with TGF-β and other ligands known to be involved in tumor-stroma crosstalk." (PMID 30442938, 2018). "Remarkably, there was also a significant positive correlation between the ADAM12 score and the CSC score in the same tumor dataset (P = 2.1E-15)." (PMID 28148288, 2017). "A positive correlation was observed between the mRNA levels of ADAM-12 and those of VEGF-A121 (P<0.0001) or VEGF-A165 (P<0.0001) in tumour samples." (PMID 16495931, 2006). "The activation status of ADAM-12 and ADAMTS-1 in tumours and corresponding control tissues was investigated by Western blotting." (PMID 16495931, 2006). "Among the inactive NBC-hom-related genes, we want to highlight the presence of proteins involved in interactions with the microenvironment, such as ADAM12, ITGA7, SH3PXD2A, and TNXB, since the tumor microenvironment is known to play a key role in MCL growth and therapy resistance." (PMID 41524027, 2026). "Notably, we confirmed that ADAM12 silencing reduces the proliferation and migration of RCC, proving its role in tumor microenvironment." (PMID 39806854, 2025). "In conclusion, high ADAM12 and CYP1B1 expressions in the peritumoral adipocytes boost tumor invasiveness and may serve as an indicator of poor prognosis in RCC." (PMID 39806854, 2025). "Additionally, significant positive correlations have been observed between ADAM12 expression and the gene expression signature of TINs/PMN-MDSCs (tumor-infiltrating neutrophils/polymorphonuclear-myeloid derived suppressor cells) in TNBC." (PMID 38317965, 2024). "This dual governing cell survival role of ADAM12 is approved by another finding, which demonstrates that ADAM12 enhances nonneoplastic cells’ apoptotic sensitivity while increasing tumor cells resistance to apoptosis." (PMID 38317965, 2024). "ADAM12, when interacting with its integrin substrates, exhibited an inverse relationship with tumor growth, whereas ADAM15’s interaction with integrin beta 3 (ITGB3) was positively correlated with tumor growth." (PMID 39519201, 2024). "Therefore, we tested prophylactic and therapeutic vaccination against ADAM12 in murine PDAC and observed delayed tumor growth along with a reduction in CAFs and tumor desmoplasia." (PMID 39478152, 2024). "In preclinical mouse models of PDAC, we observe ADAM12 expression in CAFs as well as in tumor cells but not in healthy mouse pancreas." (PMID 39478152, 2024). "We observed that, although inhibition of CAIX normalized the extracellular tumor pH to levels similar to those achieved by depletion of ADAM12+ cells, antitumor immunity was not restored." (PMID 37798557, 2023). "In contrast to some mouse studies, we observed no significant change in tumor growth or overall mouse survival upon ADAM12 knockout, possibly due to cancer type and its TME specificity." (PMID 37495855, 2023). "Treatment with CD8+ T cell-depleting antibodies restored tumor growth in the absence of ADAM12+ cells, confirming that ADAM12+ cells block antitumor activity of CD8+ T cells." (PMID 37798557, 2023). "Spermatogenesis associated 18 (SPATA18) and EF-hand domain family member D1 (EFHD1), as opposed to SPOCK1, GTSE1 and ADAM12, are two tumor suppressors both involved in mitochondria functions." (PMID 37370817, 2023). "We also evaluated the expression of LANA and the human surface markers in the spleens of the tumor-bearing mice, where no cross-reactive staining was observed except for low levels of ADAM12." (PMID 37046832, 2023). "As oxygen levels were restored in the absence of ADAM12+ cells, Car9 expression was significantly decreased in the total tumor." (PMID 37798557, 2023).